PAIP2 (poly(A) binding protein interacting protein 2)
Description:
Acts as a repressor in the regulation of translation initiation of poly(A)-containing mRNAs. Its inhibitory activity on translation is mediated via its action on PABPC1. Displaces the interaction of PABPC1 with poly(A) RNA and competes with PAIP1 for binding to PABPC1. Its association with PABPC1 results in disruption of the cytoplasmic poly(A) RNP structure organization.
Synonyms: PAIP-2; PAIP2A
Tractability: PROTAC: UniProt records ubiquitination sites on it; ubiquitination databases record sites on it; its protein half-life has been measured.
Gene: Protein-coding gene on chromosome 5 (139,341,587 to 139,369,720, forward strand). Ensembl gene ENSG00000120727.
Subcellular location: Cytoplasm
Subcellular location (Human Protein Atlas): Vesicles
Pathways (Reactome):
Developmental Biology: M-decay: degradation of maternal mRNAs by maternally stored factors
Gene Ontology:
Molecular function: protein binding; translation repressor activity; mRNA binding; mRNA regulatory element binding translation repressor activity
Biological process: negative regulation of translational initiation; negative regulation of translation
Cellular component: cytoplasm
Genetic constraint (gnomAD): Loss-of-function variants: 0 observed, 2.09 expected, observed/expected ratio (o/e) 0, 90% interval 0 to 1.31. That is too few expected variants to judge how well the gene tolerates losing a copy. Missense variants: 50 observed, 58.02 expected, observed/expected ratio (o/e) 0.86, 90% interval 0.69 to 1.09. Synonymous variants: 19 observed, 16.87 expected, observed/expected ratio (o/e) 1.13, 90% interval 0.78 to 1.64.
Homologues: Orthologues: rabbit PAIP2 (99% identical), chimpanzee PAIP2 (98% identical), guinea pig PAIP2 (98% identical), macaque PAIP2 (98% identical), pig PAIP2 (98% identical), mouse Paip2 (96% identical), rat Paip2 (84% identical), Drosophila melanogaster Paip2 (36% identical). Paralogues in human: PAIP2B (59% identical).
Diseases named in the same sentence as PAIP2 in open-access papers:
PAIP2 is named in the same sentence as 19 diseases in open-access papers, as found by Europe PMC text mining. Sharing a sentence is not in itself a finding about the gene and the disease. The quoted sentences say what the papers report.
HCMV infection (3 papers, 2014 to 2020). "Furthermore, a recent work has revealed that Paip2, whose expression is stimulated by human cytomegalovirus (HCMV) infection, limits HCMV protein synthesis and replication." (PMID 26735137, 2016). "Moreover, another study demonstrated a role of PAIP2, whose stability is regulated by UBR5/EDD1, as a restriction factor limiting productive HCMV infection." (PMID 33031466, 2020).
breast carcinoma (2 papers, 2006 to 2022). "The high expression of PAIP2 is associated with better OS in breast cancer patients and is negatively correlated with most chemotherapeutic drug sensitivity and IPS in cancer immunotherapy." (PMID 36437922, 2022). "According to the results of prognostic analysis, PAIP2 was a risk factor for RFS in breast cancer patients (HR = 1.23, 95% CI: 1.06-1.43)." (PMID 36437922, 2022). "Transwell and CCK8 experiments also confirmed that PAIP2 could promote the invasion and proliferation of breast cancer cells, which suggested that PAIP2 was a risk factor for promoting the progression of breast cancer." (PMID 36437922, 2022). "We found that PAIP2 has potential value as a diagnostic biomarker and prognostic marker for breast cancer and may predict the effect of immunotherapy for breast cancer." (PMID 36437922, 2022). "The correlation analysis between PAIP2 expression and TMB shows that PAIP2 expression is negatively correlated with TMB in breast cancer." (PMID 36437922, 2022). "In general, although there is no specific mechanism study, our study has clarified the high expression of PAIP2 in breast cancer cells and tissues, and has the role of promoting the proliferation and metastasis of breast cancer cells." (PMID 36437922, 2022). "Studies have shown that PAIP2 has higher expression in breast cancer tissues and breast cancer cells." (PMID 36437922, 2022). "RT-qRCR and Western blotting were used to verify the expression of PAIP2 in breast cancer cells and normal breast cells." (PMID 36437922, 2022). "The data of breast cancer samples were obtained in the TCGA database and the HPA database to analyze the expression of PAIP2 in breast cancer samples." (PMID 36437922, 2022). "PAIP2 can promote the proliferation and invasion of breast cancer cells and has significantly high expression in higher tumor stages." (PMID 36437922, 2022). "In breast cancer cells, the protein and mRNA expression levels of PAIP2 were higher than those in normal breast cells." (PMID 36437922, 2022). "Even if more clinical trials are needed to support PAIP2 expression as a protective factor for OS, PPS and DMFS in STAD patients, it also shows the potential value of PAIP2 as a prognostic biomarker for breast cancer patients." (PMID 36437922, 2022). "The IHC results of PAIP2 in HPA database also showed that PAIP2 was higher expressed in breast cancer than in normal breast tissues at protein level." (PMID 36437922, 2022). "And to explore the possibility of PAIP2 as a target therapy of breast cancer." (PMID 36437922, 2022). "siRNA transfection in advance reduced PAIP2 content in MCF-7 breast cancer cells." (PMID 36437922, 2022). "Interestingly, although it is clear that PAIP2 can promote breast cancer, from a longer-term perspective of OS and PPS, the PAIP2 high expression group is significantly associated with longer OS, PPS, and DMFS in breast cancer patients." (PMID 36437922, 2022). "Our study explored the potential value of PAIP2 as a biomarker for diagnosis and prognosis and may predict the efficacy of immunotherapy, providing reference for the follow-up study on the role of PAIP2 in breast cancer." (PMID 36437922, 2022). "Interestingly, VEGF-A expression is also correlated to PAIP2 protein levels in human breast cancer specimens (Onesto C., unpublished results), bringing forward the importance of PAIP2 in regulating VEGF-A expression in human cancers." (PMID 16641910, 2006). "In bioinformatics analysis, PAIP2 is found to be an influencing factor for the prognosis of breast cancer patients and may also have potential value in predicting the effect of immunotherapy for breast cancer." (PMID 36437922, 2022). "However, the role of PAIP2 in breast cancer remains unclear." (PMID 36437922, 2022). "However, the possible role of PAIP2 in the progression of breast cancer is still unknown." (PMID 36437922, 2022).
breast carcinoma (continued). "In order to verify the expression of PAIP2 in breast cancer cells in vitro, MCF-10a normal breast epithelial cells and MCF-7 breast cancer cells were used for comparison." (PMID 36437922, 2022). "Therefore, we speculate that PAIP2 may promote breast cancer by affecting VEGF, a signaling pathway that is clearly shown to play an important role in breast cancer growth and metastasis of breast cancer." (PMID 36437922, 2022).
head and neck cancer (2 papers, 2006 to 2022). A primary or metastatic malignant neoplasm affecting the head and neck. "The significant association observed in this study between VEGF-A and PAIP2 protein levels in human head and neck carcinomas supports the data we obtained in several tumour cell lines, including a pharynx carcinoma cell line (this report)." (PMID 16641910, 2006). "In head and neck squamous cell carcinoma, PAIP2 was associated with tumor growth and apoptosis, and PAIP2 was found to control the expression of VEGF-A in head and neck cancer was controlled by PAIP2." (PMID 36437922, 2022). "Hence, PAIP2 strongly regulates VEGF-A expression in a head and neck carcinoma cell line." (PMID 16641910, 2006). "PAIP2 is also a VEGF mRNA 3 ' -UTR interacting protein, can regulate the expression of VEGF, such as in head and neck cancer." (PMID 36437922, 2022). "Our data suggest that, in contrast to PAIP2 protein levels, which are unrelated to tumour prognosis, VEGF-A expression could serve as a prognostic marker in head and neck cancer and may be helpful for targeted therapies." (PMID 16641910, 2006). "Prior to analysis for a potential correlation between PAIP2 and VEGF-A expression in the 54 HNSCC specimens, we first checked whether the effect of PAIP2 on VEGF-A expression also occurs in a head and neck carcinoma cell line." (PMID 16641910, 2006).
Alzheimer disease (1 paper, 2016). A progressive, neurodegenerative disease characterized by loss of function and death of nerve cells in several areas of the brain leading to loss of cognitive function such as memory and language. "For example, ciRS-7 was found to be a natural microRNAs sponge for miRNA-7 and regulate Parkinson’s disease/Alzheimer’s disease-related genes; circPAIP2 is an intron-retaining circRNA which upregulates memory-related parental genes PAIP2 to affect memory development through PABP reactivation." (PMID 27092176, 2016).
brain tumor (1 paper, 2023). "Supporting this hypothesis, our dataset discloses several RNA biding molecules and translation inhibitors—Syncrip (Syp), musashi (msi), pumilio (pum), brain tumor (Brat), or polyA-binding protein interacting protein 2 (Paip2)—to be expressed in Phase 1 and Phase 2 neurons." (PMID 37205703, 2023).
cervical cancer (1 paper, 2020). A primary or metastatic malignant neoplasm involving the cervix. "It has been demonstrated that circ-EIF3J, circ-PAIP2, and circ-FUNDCl are significantly overexpressed in cervical cancer cells." (PMID 33312941, 2020).
leukoplakia (1 paper, 2014). A white patch or plaque on a mucous membrane that cannot be characterized clinically or pathologically as any other disease. "Amplified genes mapping within recurrent CNAs (KHDRBS1, PARP1, RAB1A, HBEGF, PAIP2, BTBD7) were selected for validation, by quantitative real-time PCR, in an independent set of 32 progressive leukoplakia, 32 OSSCs and 21 non-progressive leukoplakia samples." (PMID 24403051, 2014).
male infertility (1 paper, 2021). The inability of the male to effect fertilization of an ovum after a specified period of unprotected intercourse. "Among these RHOX10-direct target genes was Paip2, which encodes a translational repressor protein, whose loss leads to male infertility." (PMID 34289349, 2021).
pharynx carcinoma (1 paper, 2006). A primary or metastatic malignant neoplasm that affects the pharynx. "To this end, we silenced PAIP2 expression by RNA interference in Detroit 562 cells derived from a human pharynx carcinoma." (PMID 16641910, 2006). "In a pharynx carcinoma cell line, we demonstrated by RNA interference that VEGF-A expression is closely controlled by PAIP2." (PMID 16641910, 2006).
tumor (6 papers, 2006 to 2022). "We then investigated whether PAIP2 expression is associated with VEGF-A expression in the human tumour samples." (PMID 16641910, 2006). "According to the RNA-seq difference analysis of normal tissues and tumor tissues in TCGA database and GTEx database, PAIP2 is highly expressed in BRCA tissues compared with normal breast tissues." (PMID 36437922, 2022). "Using bioinformatics technology to explore the prognostic value of PAIP2 and its possible biological function, and its effect on tumor immunity and immunotherapy." (PMID 36437922, 2022). "Because it is a negative regulator of Pabp activity and of protein synthesis, Paip2 can therefore function as inhibitor of cellular transformation and a tumor suppressor." (PMID 21957478, 2011). "We determined the correlation of VEGF-A and PAIP2 protein levels, quantitatively evaluated in tumour tissue homogenates from 54 patients with HNSCC, to clinicopathological parameters." (PMID 16641910, 2006). "By univariate analysis, we investigated the correlation between PAIP2 expression and clinicopathological tumour parameters." (PMID 16641910, 2006). "Our results showed that enforced expression of miR-128 inhibited the HNSCC cell proliferation and tumor xenograft growth by mediating the expression of BMI-1, BAG-2, BAX, H3f3b, and Paip2 mRNAs, suggesting that miR-128 might act as a tumor suppressor." (PMID 25764126, 2015). "Therefore the ability of Paip2 to function as a tumor suppressor is dependent upon its ability to interact with Pabp." (PMID 21957478, 2011). "We could imagine that any dysregulation of PAIP2 expression could explain the abnormal VEGF-A protein levels in a tumour context." (PMID 16641910, 2006). "Therefore it is possible that Paip2 may function as a tumor suppressor as over production of the protein delays progression through the cell cycle." (PMID 21957478, 2011). "Paip2, Bmi-1, and H3F3B proteins are involved in tumor growth, and downregulation of Bmi-1 and H3F3B expression reduces cancer growth and xenograft development in JHU-22 miR-128 cells." (PMID 36793341, 2022). "The observations from this study, that up-regulation of miR-128 inhibited HNSCC growth through directly mediating its targets Paip2, BAG-2, H3F3B, BMI-1, and BAX in proliferation and apoptotic pathways, support that miR-128 functions as a tumor suppressor." (PMID 25764126, 2015). "Moreover, we have recently demonstrated in several tumour cell lines that VEGF-A expression is highly regulated by an RNA-binding and stabilizing partner of the VEGF-A mRNA, the Poly(A) binding protein-interacting protein 2 (PAIP2)." (PMID 16641910, 2006). "No statistical significance was found between all these clinicopathological variables and the degree of PAIP2 expression in tumour tissues (data not shown)." (PMID 16641910, 2006). "Hence, despite its strong correlation with VEGF-A protein levels, PAIP2 expression is neither a prognostic factor for tumour progression nor for patient's outcome in the 54 human HNSCC analyzed." (PMID 16641910, 2006).
cancer (3 papers, 2006 to 2022). A tumor composed of atypical neoplastic, often pleomorphic cells that invade other tissues. "PAIP2 was also helpful for cancer cell migration in Transwell chamber migration experiment, which was also statistically significant." (PMID 36437922, 2022). "CCK8 results showed that the decrease of PAIP2 expression would help to reduce the proliferation of cancer cells, and it was statistically significant." (PMID 36437922, 2022). "Continued understanding how of the interactions of Paip2 and Pabp, and of Paip2 and EDD1 are regulated should augment our understanding of how efficient translation initiation is controlled and promote the development of novel anti-cancer therapeutic agents." (PMID 21957478, 2011).
PAIP2 also shares sentences with these, for which no sentence is quoted: cervix adenocarcinoma (1 paper); epidermoid carcinoma (1); head and neck squamous cell carcinoma (1); head and neck tumour (1); infection (1); infertile (1); Parkinson disease (1); viral infection (1).